MIAT (myocardial infarction associated transcript)
Diseases named in the same sentence as MIAT in open-access papers (continued):
Sharing a sentence is not in itself a finding about the gene and the disease.
gastric cancer (22 papers, 2018 to 2025). A primary or metastatic malignant neoplasm involving the stomach. "Myocardial infarction-associated transcript (MIAT), another lncRNA, has been shown to promote gastric cancer growth and metastasis by regulating the miR-141/DEAD-box RNA helicase 5 (DDX 5) pathway." (PMID 35123522, 2022). "Among these m6A-related eRNAs in the risk model, MIAT has been reported as a carcinogenic agent in a variety of tumors (such as gastric cancer, hepatocellular carcinoma, colorectal cancer, ovarian cancer, breast cancer, etc.)." (PMID 36230580, 2022). "We investigated MIAT expression level in 120 patients with gastric cancer and measured their associations with clinicopathological factors." (PMID 29540201, 2018). "According to another study, serum exosomal myocardial infarction associated transcript (MIAT) levels were remarkably upregulated in patients diagnosed with gastric cancer (GC) in comparison to individuals with gastric adenoma and healthy controls." (PMID 39925739, 2025). "lncRNA MIAT, a sponge for miR‐29a‐3p, regulated the biological behaviors of gastric cancer cell by up‐regulating HDAC4 expression." (PMID 31984680, 2022). "It has been reported that lncRNA MIAT acts as an oncogene upregulated in various cancers such as gastric cancer, liver cancer, colorectal cancer, and lung cancer." (PMID 34094941, 2021). "Partially in accordance with this finding, MIAT expression has been detected to be upregulated in the exosomes derived from serum samples of gastric cancer patients, and the serum exosomal MIAT can accelerate the progression of this cancer." (PMID 34459123, 2021). "Knockdown of MIAT suppresses cell biological behaviours in gastric cancer via a mechanism involving the miR-29a-3p/HDAC4 axis." (PMID 33154765, 2020). "In other studies, MIAT was identified as an oncogenic lncRNA that promoted colorectal and gastric cancers by targeting miR-132 and miR-14119,20." (PMID 30967527, 2019). "For example, it was reported that MIAT regulates cell proliferation, migration, and invasion in gastric cancer through a mechanism involving the miR-29a-3p/HDAC4 axis." (PMID 31886187, 2019). "The expression level of MIAT in gastric cancer patients were significantly correlated with differentiation degree, TNM stage, lymph node metastasis, and distant metastasis (p < 0.05)." (PMID 29540201, 2018). "In gastric cancer, MIAT promotes the metastasis of cancer cells by mediating the expression of miR-141; in ovarian cancer, MIAT is involved in modulating the invasive process of cancer cells; and in breast cancer cells, lncRNA TINCR and MIAT can regulate cell invasion, proliferation, and apoptosis." (PMID 37025425, 2023). "In addition, tissues and cell lines of gastric cancer overexpress the lncRNA MIAT which sequesters the miRNA miR-141, a negative regulator of DDX5 expression." (PMID 35954483, 2022). "Moreover, MIAT upregulation has been observed in the EVs derived from serum samples of gastric cancer patients." (PMID 34459123, 2021). "Two other targets have been reported to serve roles in gastric cancer downstream of MIAT." (PMID 33154765, 2020). "Moreover, MIAT promotes gastric cancer growth and metastasis via regulation of the miR-141/DDX5 pathway." (PMID 33154765, 2020). "The result showed that MIAT level was significantly increased in gastric cancer tissue." (PMID 29540201, 2018). "Real-time PCR was used to determine MIAT level in 120 GC tissues, and in two gastric cancer cell lines." (PMID 29540201, 2018). "Furthermore, the regulation between MIAT/miR-29a-3p/HDAC4 was recognized to be involved in cell biological behavior and the development of gastric cancer." (PMID 36620092, 2022). "Thus, high levels of MIAT result in inhibition of miR-141 synthesis and increased levels of DDX5, promoting cell proliferation and metastasis in gastric cancer." (PMID 35954483, 2022).
gastric cancer (continued). "In gastric cancer (GC), MIAT sponges miR-141, leading to an increased expression of DEAD-box RNA helicase 5 (DDX5) and influencing GC cell proliferation and migration." (PMID 37624039, 2023).
breast cancer (20 papers, 2017 to 2025). A primary or metastatic malignant neoplasm involving the breast. "MIAT has been proved to be highly expressed in breast cancer, and its aberrant expression is implicated in the clinical characteristics of patients with breast cancer." (PMID 37025425, 2023). "We found low expression of the lncRNA MIAT was associated with poor prognosis in all breast cancer subtypes." (PMID 34209776, 2021). "GOMAFU/MIAT (myocardial infarction associated transcript) is of particular interest in breast cancer since its expression is up-regulated in high-grade tumors compared with low-grade ones." (PMID 29914974, 2018). "To further confirm our observations that silencing MIAT is associated with an increase in apoptosis levels in breast cancer cells, we examine the influence of MIAT silencing on the cell survival of another TNBC cell line Hs58T." (PMID 29914974, 2018). "Our results further support such observations and confirm that MIAT down-regulation is associated with enhanced basal apoptosis levels and a decrease in short- and long-term survival of different types of breast cancer cells." (PMID 29914974, 2018). "In this study, we found that the lncRNA myocardial infarction associated transcript (MIAT) expression was upregulated in breast cancer in The Cancer Genome Atlas (TCGA) data sets." (PMID 29100300, 2017). "In breast cancer, many lncRNAs such as MIAT (myocardial infarction-associated transcript), SNHG1 (small nucleolar RNA host gene 1), and MALAT1 (metastasis-associated lung adenocarcinoma transcript 1) have been reported to participate in the occurrence, progression, and metastasis of tumors 27-29." (PMID 31892853, 2020). "Likewise, Myocardial infarction associated transcript (MIAT) also regulates p16 expression in breast cancer cells." (PMID 31141943, 2019). "Together, the data suggest that increased MIAT expression levels might be associated with an increase in the metastatic ability of breast cancer." (PMID 29914974, 2018). "Our above results suggested that MIAT upregulation may be associated with the occurrence and metastasis of breast cancer." (PMID 29100300, 2017). "Moreover, suppression of MIAT can cause G1 arrest in breast cancer cells, and MIAT may participate in tumorigenesis via regulation of the cell cycle." (PMID 37025425, 2023). "Functional studies have previously reported reduced MIAT expression levels inhibiting cell proliferation in breast cancer cells and malignant B cells." (PMID 38255915, 2024). "MIAT is overexpressed in breast cancer, and its inhibition triggers senescence and G1 arrest in MCF7 cell lines." (PMID 39456830, 2024). "This study identified 11 key methylation-driven lncRNAs (DIO3OS, ELOVL2-AS1, MIAT, LINC00536, C9orf163, AC105398.1, LINC02178, MILIP, HID1-AS1, KCNH1-IT1, and TMEM220-AS1) closely associated with breast cancer prognosis through three machine learning methods." (PMID 39456830, 2024). "In conclusion, this research confirms that MIAT is highly expressed but miR-378a-5p expression is low in breast cancer cells, and MIAT silencing inhibits the viability and proliferation of breast cancer cells by promoting the expression of miR-378a-5p." (PMID 37025425, 2023). "Herein, we explored the interaction mechanism of miR-378a-5p and MIAT in breast cancer, with the aim of uncovering a new molecular mechanism of breast cancer development and providing novel cues for the treatment of breast cancer." (PMID 37025425, 2023). "Although the role of MIAT in breast cancer has been partially reported, its regulatory mechanism needs to be further analyzed." (PMID 37025425, 2023). "Collectively, MIAT was found to be involved in regulating the development of breast cancer, but its specific role still needed further exploration." (PMID 37025425, 2023).
breast cancer (continued). "Analogous to these findings, our experimental results uncovered that inhibition of MIAT reduced breast cancer cell viability and proliferation, but further verification still needed to be conducted at the molecular level." (PMID 37025425, 2023). "After analyzing the relationship between miR-378a-5p and MIAT expressions in breast cancer tissues and normal tissues, we further found that their expressions were evidently negatively correlated." (PMID 37025425, 2023). "Extensive studies have demonstrated that LncRNA MIAT was abundant in diverse diseases including breast cancer, melanoma and non‐small cell lung cancer, while silencing LncRNA MIAT suppressed cancer cell proliferation, migration and invasion." (PMID 34967706, 2022). "Up-regulation of MIAT has been found in breast cancer cell lines and breast tumor samples compared to the normal breast tissue." (PMID 34209776, 2021). "Silencing of MIAT increases cellular senescence, apoptosis and decreases migration of breast cancer cells with elevated levels of p16, COX-2, miR-302 and miR-150 and downregulation of miR-29c." (PMID 31141943, 2019). "Our study further extends these findings and shows, for the first time, that MIAT not only regulates basal apoptosis levels, but also modulates the response of breast cancer cells to a range of apoptotic stimuli." (PMID 29914974, 2018). "A role of MIAT lncRNA in breast cancer is also emerging; studies have reported an increased MIAT expression levels in advanced breast tumors, where its overexpression was shown to be associated with lymph node metastasis." (PMID 29914974, 2018). "Reduced levels of MIAT inhibited short- and long-term survival, increased basal apoptosis, and enhanced breast cancer cell apoptotic response to a range of apoptotic stimuli in an additive way." (PMID 29914974, 2018). "Reduced levels of MIAT augmented the apoptotic response of breast cancer cells to a wide range of apoptotic stimuli." (PMID 29914974, 2018). "In the present study, we have focused on the implications of reduced MIAT expression on the response to different cell death stimuli in breast cancer cells." (PMID 29914974, 2018). "Emerging evidence suggests that MIAT expression levels are increased in different type of cancers, including breast cancer." (PMID 29914974, 2018). "Expression levels of MIAT mRNA in breast cancer were determined using TissueScanTM Breast Cancer cDNA Arrays." (PMID 29914974, 2018). "The influence of MIAT silencing on the short- and long-term survival of breast cancer cells was examined under basal conditions." (PMID 29914974, 2018). "While the effects of down-regulation of MIAT expression levels on breast cancer cell survival have been examined, the consequences of reduced MIAT levels for chemotherapeutic drug action in breast cancer cells have not been examined to-date." (PMID 29914974, 2018). "Functional studies have previously reported that MIAT regulates cancer cell survival, with decreased MIAT expression levels inhibiting cell proliferation in breast cancer cells and malignant B cells." (PMID 29914974, 2018). "The increase in MIAT expression levels was more enhanced in the TNBC samples, consistent with the observations that MDA-MB-231 TNBC cell line showed the highest expression levels of MIAT when compared with other breast cancer cell lines." (PMID 29914974, 2018). "In the present study, we further evaluated the role of MIAT in breast cancer and investigated the consequences of its silencing on breast cancer response to chemotherapeutic agents." (PMID 29914974, 2018). "We detected MIAT mRNA in 30 paired breast cancer tissues by RNA Scope® 2.0 technology and found that MIAT mRNA was higher in breast cancer tissues than in normal breast tissues (P<0.05)." (PMID 29100300, 2017).
breast cancer (continued). "The results revealed that MIAT was upregulated in breast cancer tissues than in normal breast tissues (P<0.05) and in paired case-control analysis MIAT expression was still upregulated in breast cancer tissues (P<0.05)." (PMID 29100300, 2017). "We validated that MIAT was higher in breast cancer cell lines and advanced breast tumors than in normal controls." (PMID 29100300, 2017). "Our studies have revealed that the lncRNA MIAT is highly upregulated in breast cancer cell lines and breast cancer tissues." (PMID 29100300, 2017). "Our results suggested that MIAT acted as a competing endogenous RNA (ceRNA) to regulate the expression of dual specificity phosphatase 7 (DUSP7) by taking up miR-155-5p in breast cancer." (PMID 29100300, 2017). "We conclude that MIAT promotes breast cancer progression and functions as ceRNA to regulate DUSP7 expression by sponging miR-155-5p in breast cancer." (PMID 29100300, 2017). "To understand the mechanism of MIAT regulation in breast cancer, we indicated that MIAT shared miR-155-5p response element with DUSP7, which belongs to DUSP family." (PMID 29100300, 2017). "Using bioinformatics methods, we also found that MIAT expression was higher in breast cancer tissues than in normal breast tissues from The Cancer Genome Atlas (TCGA) breast cancer data sets." (PMID 29100300, 2017). "The results suggested that MIAT expression was higher in breast cancer patients with TNM III stage (P<0.01)." (PMID 29100300, 2017). "Future studies will investigate the mechanisms of MIAT in breast cancer and the utility of MIAT as potential specific therapeutic target." (PMID 29100300, 2017). "The results suggested that MIAT functions as oncogene partly through influencing DUSP7 expression in breast cancer through miR-155-5p." (PMID 29100300, 2017). "We also validated that the expression of MIAT was higher in breast cancer cell lines and advanced breast tumors than in normal controls." (PMID 29100300, 2017). "As a result, anti-PD-1/anti-PD-L1 immunotherapy may emerge as a promising therapeutic strategy for breast cancer characterized by elevated MIAT expression." (PMID 40149989, 2025). "MIAT is a long non-coding RNA whose expression levels vary in different breast cancers." (PMID 39911848, 2025). "MIAT silencing could decrease Bcl-2 expression, viability, and proliferation of breast cancer cells and increase the expressions of cleaved caspase-3 and Bax." (PMID 37025425, 2023). "According to the results, MIAT was highly expressed in breast cancer tissues and cells." (PMID 37025425, 2023). "Similarly, qRT-PCR results also indicated that MIAT expression was increased in breast cancer cell lines when a comparison was made with that in the normal breast epithelial cell line MCF-10A." (PMID 37025425, 2023). "In addition, it has been reported that MIAT silencing induces the apoptosis of breast cancer cells and enhances cell sensitivity to chemotherapy drugs." (PMID 37025425, 2023). "Likewise, MIAT is highly expressed in breast cancer, and inhibition of MIAT can repress breast cancer cell migration and proliferation and promote apoptosis." (PMID 37025425, 2023). "In conclusion, MIAT silencing inhibits the viability and proliferation of breast cancer cells by promoting miR-378a-5p, indicating the potential of MIAT as a new target for the treatment of breast cancer." (PMID 37025425, 2023). "We determined the expression of MIAT in human breast cancer tissues and normal tissues by qRT-PCR." (PMID 37025425, 2023). "We found few reports in the literature addressing the role of MIAT in breast cancer." (PMID 34209776, 2021). "For instance, MIAT was significantly higher in breast cancer (BC) cell lines and high‐grade tumors." (PMID 32274858, 2020). "Our findings indicate that MIAT expression level is increased in breast cancer." (PMID 29914974, 2018).
breast cancer (continued). "Strategies to decrease MIAT expression levels may improve sensitivity to therapy in breast cancer by enhancing the apoptotic responses to conventional chemotherapies." (PMID 29914974, 2018). "MIAT transcript levels were significantly elevated in breast cancer samples." (PMID 29914974, 2018). "In breast cancer cells, MIAT knockdown inhibits cell proliferation and stimulates apoptosis." (PMID 29914974, 2018). "The present study shows that MIAT lncRNA is up-regulated in breast cancer and in particular in TNBC, suggesting that MIAT may act as oncogene." (PMID 29914974, 2018). "The effects of MIAT down-regulation on promoting apoptosis could have implications for breast cancer therapy, since the mode of action of many chemotherapeutic drugs is largely dependent on their interaction with apoptotic signaling pathways." (PMID 29914974, 2018). "First, we have evaluated the expression of MIAT in samples from different stages of breast cancer." (PMID 29914974, 2018). "Indeed, reduced levels of MIAT expression decreased migration and invasion in breast cancer cells and inhibited human breast tumor growth in a xenograft mouse model, suggesting that MIAT acts as an oncogene." (PMID 29914974, 2018). "MIAT was found to be a key regulator of breast cancer cell survival." (PMID 29914974, 2018). "To further extend this finding, we investigated that MIAT acted as a ceRNA to regulate DUSP7 mRNA by taking up miR-155-5p in breast cancer cells, which might be one of the mechanisms of MIAT functions as an oncogene." (PMID 29100300, 2017). "There were positive correlation between DUSP7 expression and MIAT in breast cancer patients." (PMID 29100300, 2017). "Moreover, MIAT expression level was positively associated with advanced TNM stage and lymphnode metastasis in breast cancer patients." (PMID 29100300, 2017). "In summary, our data suggested that MIAT may serve as an oncogene in breast cancer and promote breast cancer progression through interacting with miR-155-5p." (PMID 29100300, 2017). "We proposed that MIAT acted as a ceRNA to regulate DUSP7 mRNA by taking up miR-155-5p in breast cancer cells, which might be one of the mechanisms of MIAT as an oncogene." (PMID 29100300, 2017). "In this study, we found MIAT was upregulated in breast cancer in TCGA data sets." (PMID 29100300, 2017). "Furthermore, knockdown of MIAT inhibited breast cancer cell proliferation, migration, invasion and EMT but promoted the rate of apoptosis." (PMID 29100300, 2017). "Knockdown MIAT inhibited breast cancer cell proliferation and promoted apoptosis." (PMID 29100300, 2017). "Then we studied the molecular mechanism of MIAT in breast cancer." (PMID 29100300, 2017). "Furthermore, down regulation of MIAT decreased tumor growth and delayed tumor formation in vivo, suggesting that MIAT might promote breast cancer malignant progression." (PMID 34209776, 2021). "Similarly, MIAT was dominantly expressed in ER/PR/HER2+ breast cancers samples." (PMID 30959550, 2019). "Similar to breast cancer, our literature search uncovered several high ranked lncRNAs that are linked to blood cancers but yet not been added to the LncRNADisease database, such as MIAT, MALAT1, XIST, CRNDE." (PMID 31379598, 2019). "Finally, we have investigated the hypothesis that reduction in MIAT expression levels enhances the response of breast cancer cells to cell death-inducing stimuli, including chemotherapeutic drugs and ultraviolet-C (UV-C)." (PMID 29914974, 2018). "The findings that reduced levels of MIAT enhanced both basal apoptosis of breast cancer cells and their response to a range of apoptotic stimuli could therefore have important clinical significance in relation to the response of breast tumors to cytotoxic therapy." (PMID 29914974, 2018). "We analyzed whether MIAT could function as ceRNA in breast cancer." (PMID 29100300, 2017). "The data suggested that MIAT knockdown could inhibit EMT of breast cancer cells." (PMID 29100300, 2017).